CXCR4 (C-X-C motif chemokine receptor 4)
Diseases named in the same sentence as CXCR4 in open-access papers (continued):
Sharing a sentence is not in itself a finding about the gene and the disease.
tumor (continued). "Akt1-associated CXCL12/CXCR4 signaling promotes tumor growth, suggesting that Akt inhibitors may potentially be employed as anticancer agents to target expansion of PC bone metastases." (PMID 23902739, 2013). "The goal of the present study was to determine whether anti-cancer agent emodin can modulate the expression and function of CXCR4, a chemokine receptor that has been closely linked with tumor cell proliferation, invasion, and metastasis." (PMID 23472074, 2013). "However, the exact role of and mechanisms by which the CXCL 12/CXCR4 axis in GSCs promotes tumor proliferation and tumor-associated neovascularization remain ambiguous, and corresponding therapeutic treatments have yet to be identified." (PMID 23961808, 2013). "In both models, SDF-1/CXCR4 signaling was implicated as a mediator of wound-promoted tumor growth, demonstrating that this signaling pathway can mediate adverse effects of surgery on tumor growth." (PMID 23593347, 2013). "The aim of the present study was to determine whether the anti-cancer agent, plumbagin, can suppress the expression and function of CXCR4, a chemokine receptor that has been closely linked with tumor cell proliferation, invasion, and metastasis." (PMID 21880153, 2011). "We hypothesise that elevated levels of tumour SDF-1 caused by increased tumour hypoxia (resulting from gradual loss of ECs) following irradiation lead to accumulation of CXCR4-expressing monocytes/macrophages in the irradiated tumour." (PMID 21587260, 2011). "Loss of DNA methylation in the promoter region of CXCR4 correlated with a more aggressive disease in terms of tumor stage, tumor size, SBR grade, 5demonstrated that concurrent epigenetic changes of CXCR4 and its ligand, CXCL12, correlated with shorter disease-free and overall survivals." (PMID 22220212, 2011). "Beside the effect on tumour dissemination, CXCR4 as well as other chemokine receptors have also been implicated in various aspects of tumour progression such as cancer cell proliferation and survival as well as in the regulation of the leukocytic and endothelial milieu within the tumour environment." (PMID 19436305, 2009). "Dataobtained from in vitro as well as from murine in vivo models, analyzing themetastatic ability of CXCR4 in expressing cancer cells, underlined thekey role of CXCR4 for tumor cell malignancy, as activation of CXCR4 by SDF-1α induced migration, invasion, and angiogenesis of cancercells." (PMID 19266088, 2008). "SDF1/CXCR4 interactions also underly other long-range migration events such as the movement of germ cells both in fish and in mouse, the migration of facial motoneurons in fish and the movement of tumor cells in the formation of metastases." (PMID 17394634, 2007). "The activation of CXCR4 may recruit at least one of a number of immunosuppressive cells, including regulatory T cells (Tregs), myeloid-derived suppressor cells (MDSCs), and tumour-associated macrophages (TAM), that inhibit cytotoxic T cell responses and facilitate tumour growth." (PMID 41002447, 2025). "Moreover, CXCR4 suppression has also been associated with increased tumor cell death." (PMID 36986504, 2023). "Therefore, proliferative activity and loss of original conformation, mediated by CXCR4, could promote poor tumor differentiation." (PMID 37697316, 2023). "Moreover, different CXCR4 localizations and geographical areas might be resources causing the high heterogeneity of tumor stage." (PMID 35729596, 2022). "Previous studies have shown that nuclear expression of CXCR4 is associated with better survival than cytomembranous expression, and this might be due to less tumor-promoting effects of the receptor with nuclear localization compared to when the receptor is in the cytomembranous compartment." (PMID 33507926, 2021).
tumor (continued). "In future studies, it is imperative to obtain tumor biopsies to confirm the hypothesis that CXCR4 inhibition is associated with increased T cell trafficking to the tumor microenvironment, and further evaluate 40 mg dose as the appropriate dose to accomplish this task." (PMID 32219196, 2020). "Although chemokines derived from infiltrated dendritic cells were not confirmed to be involved in cancer pain in the current research, other cells such as macrophages in tumor microenvironment might generate massive CXCL12 to sensitize pain associated with cancers via interacting with CXCR4 in DRG." (PMID 32434423, 2020). "However, there is evidence that CXCR4 blockade per se might cause deleterious mobilization of both cancer cells and tumour-promoting, infiltrating stromal/immune cells." (PMID 30792442, 2019). "Thus, PB cfDNA could become a useful tool for the initial assessment of MYD88L265P and CXCR4 mutations by reflecting the overall tumor burden in patients with WM." (PMID 30026568, 2018). "Dimerization of CXCL12 as the ligand of CXCR4 is important as it stimulates intracellular calcium flux but fails to activate F-actin polymerization or β-arrestin 2 recruitment which has been shown to cause cellular idling that blocks the metastatic tumour formation." (PMID 28775330, 2017). "Notably, we proved that CXCR4-linked tumor burden occurred in a zebrafish Cxcl12-dependent manner." (PMID 26744352, 2016). "Moreover, VEGF produced by tumor cells may induce CXCR4 expression in the tumor cell itself and/or in tumor-associated endothelial cells that facilitate both angiogenesis and metastasis of the primary tumor." (PMID 25605248, 2015). "We investigated whether the mRNA expression of IL-6 in the control tumor xenografts had any correlation with the mRNA levels of invasion-associated genes such as CXCR4, MMP-2, and MMP-9 in response to systemic administration of paclitaxel and oral gavages of CYT387." (PMID 24782986, 2014). "Furthermore, CXCL12 is also indirectly implicated in tumor pathogenesis, acting as chemoattractant for CXCR4-positive cells, directing tumor cell migration and controlling invasive and metastatic properties of CXCR4-expressing cancer cells to distant organs." (PMID 25484899, 2014). "Importantly, MIF and CXCR4 expression levels in tumor cells and in TILs were positively associated." (PMID 23497377, 2013). "However, it is not known whether Akt activation downstream of PTEN loss regulates CXCL12/CXCR4 expression and function in tumor cells." (PMID 23902739, 2013). "CAIX, GLUT1, and CXCR4 prevalence rates significantly increased with histological grade, which is consistent with the hypothesis that high grade tumors have a higher proliferation rate, causing neo-angiogenesis to lag behind tumor growth." (PMID 24206539, 2013). "Moreover, it seems relevant to remind that CXCR4 expression has been associated to a worse prognosis in human tumours, and then, in the future, it could be also used as prognostic indicator." (PMID 22417013, 2012). "PAX3- and PAX7-FKHR gene fusion, mutations in the von Hippel Lindau tumor suppressor gene, hypoxia in the tumor microenvironment, NF-κB, and inflammatory cytokines such as vascular endothelial growth factor and tumor necrosis factor alpha, have all been implicated in CXCR4 overexpression." (PMID 21880153, 2011). "In addition, using a virtual, predictive, functional proteomics-based tumor pathway platform, we tested the hypothesis that NF-κB inhibition by plumbagin causes the decrease in CXCR4 and other metastatic genes." (PMID 21880153, 2011).
tumor (continued). "In addition, studies have also suggested that CXCL12/CXCR4 may indirectly promote tumor metastases by mediating proliferation of tumor cells and enhancing tumor-associated angiogenesis." (PMID 17083723, 2006). "AMD3100 (10 mg/kg) was administered intraperitoneally to LLC1‐bearing mice at ZT4 or ZT16, corresponding to the time points just before the trough and peak of CXCR4 expression in tumor‐infiltrated CD8+ T cells, respectively." (PMID 41257391, 2026). "The CXCL12/CXCR4 axis also orchestrates interactions with the tumor microenvironment, facilitating chemotaxis toward CXCL12-rich niches (e.g., bone marrow and brain) and modulating anti-tumor immunity via regulatory cells." (PMID 41750259, 2026). "The findings indicate that CXCR4 expression in tumor‐infiltrated CD8+ T cells is upregulated in patients with NSCLC." (PMID 41257391, 2026). "Intraperitoneal administration of LY364947 (25 mg/kg), a TGF‐β receptor inhibitor, to LLC1 tumor‐bearing mice decreased Cxcr4 mRNA and protein expression levels in tumor‐infiltrated CD8+ T cells." (PMID 41257391, 2026). "Temporal elevation of CXCR4 expression on tumor‐infiltrated CD8+ T cells promoted their migration toward CXCL12‐expressing cancer‐associated fibroblast (CAFs) high‐density regions, which are distant from cancer cells." (PMID 41257391, 2026). "Preclinical studies have confirmed that CXCR4 blockade can reduce Tregs and MDSCs infiltration and enhance antitumour immunity across multiple tumour types." (PMID 41601679, 2026). "The incorporation of CXCR4 increases immunosuppression activity in the tumor microenvironment, and CXCR4-targeted therapies can reverse this process." (PMID 41489768, 2026). "To elucidate the mechanisms driving CXCR4 upregulation in tumor‐infiltrated CD8+ T cells, we performed pathway enrichment and hypergeometric optimization of motif enrichment (HOMER) motif analyses." (PMID 41257391, 2026). "Our findings reveal that tumor-stroma crosstalk via the CXCL12/CXCR4/BMI1 axis plays a central role in sustaining miCSC-driven metastasis and therapy resistance in PDAC." (PMID 41991735, 2026). "Se@A&F induced CAFs' inactivation and remodeled the tumor microenvironment by down-regulating CXCR4 expression on CAFs' surface and inhibiting the CXCL12/CXCR4 signaling axis." (PMID 41328341, 2026). "This tumor cell-driven hijacking of CXCR4 signaling provides a spatial mechanism for TME reprogramming and immunotherapy resistance." (PMID 41355948, 2026). "The expression levels of CXCR4 mRNA were increased in CD8+ T cells collected from tumor tissues (TTC) compared to those from adjacent normal lung tissues (NTC) or peripheral blood (PTC)." (PMID 41257391, 2026). "The amplitude of the Cxcr4 expression rhythm was more pronounced in tumor‐infiltrated T cells than in those from the spleen and was associated with time‐dependent changes in their migration toward CXCL12‐expressing cancer‐associated fibroblasts (CAFs)." (PMID 41257391, 2026). "The CXCL12/CXCR4 axis is crucial in tumor progression, especially due to its role in tumor angiogenesis, cancer cell metastasis and survival." (PMID 40211853, 2026). "The translational challenge in regard to effective blockade of CXCR4 in tumours while minimising both systemic adverse events will be key for the future development of CXCR4 blockade therapies." (PMID 41002447, 2025). "CXCR4 is increasingly recognized not only for tumor visualization but also for its ability to assess tumor heterogeneity and resistance mechanisms—particularly in CSC-rich cancers." (PMID 39753364, 2025). "Among them, gemcitabine (p = 0.001820) inhibits tumor cell migration by targeting the CXCL12/CXCR4 axis, potentially suppressing monocyte infiltration into atherosclerotic plaques through a similar mechanism." (PMID 41283645, 2025). "Pharmacokinetic data confirmed effective plerixafor penetration into cerebrospinal fluid and tumor tissue, achieving therapeutic CXCR4-inhibiting concentrations." (PMID 40427130, 2025).
tumor (continued). "[68Ga]Ga-Pentixafor and [177Lu]Lu-Pentixather are pioneer tracers for the detection and treatment of CXCR4-positive tumours." (PMID 39747850, 2025). "As previously discussed, the CXCL12/CXCR4 regulatory axis plays a critical role in homing and retention within the protective bone marrow microenvironment for hematologic tumor cells and normal hematopoietic stem cells (HSCs)." (PMID 40427609, 2025). "This strategy successfully induced CXCR4+ macrophages polarization into M1 tumor-suppressive phenotype in a mouse model of triple-negative breast cancer, offering a dual-targeted therapeutic effect." (PMID 40307933, 2025). "Previous studies on inhibiting CXCR4 have primarily focused on metastasis and tumor invasion, with limited investigation into its role in neovascularization, particularly in OSCC." (PMID 41210695, 2025). "Our key findings are that CXCR4 blockade attenuates osteoclast activation at the tumor-bone interface and concurrently inhibits the epithelial-mesenchymal transition (EMT) program within cancer cells." (PMID 41413548, 2025). "Concurrently, this axis creates an “immune-excluded” phenotype by using stromal CXCL12 to sequester CXCR4-positive T cells, preventing their infiltration into tumor nests." (PMID 40909268, 2025). "CXCR4/CXCL12 also facilitates the homing of tumour cells to distal organs while limiting therapeutic effectiveness due to protecting tumour cells from immune attack and apoptosis, making it an important therapeutic target." (PMID 41002447, 2025). "Recent studies have shown that inhibiting CXCR4 or CXCL12 can enhance tumor immunity by promoting CD8+ T-cell retention." (PMID 40141028, 2025). "The CXCL12–CXCR4 axis drives the recruitment of CXCR4‐expressing tumor cells to CXCL12‐rich organs such as the lungs, facilitating metastatic seeding through chemotactic migration." (PMID 40470380, 2025). "Increased expression levels of CXCR4 have been connected to greater osteotropism in tumor cells, suggesting its potential as a predictive biomarker." (PMID 40426987, 2025). "These nanoplexes, targeted both tumor cells (through CXCR4 antagonism) and macrophages (via miR-127 delivery) to modulate the tumor microenvironment." (PMID 40307933, 2025). "Circulating levels of certain chemokines, particularly CXCL12 and CXCR4, have been investigated as potential biomarkers for tumor grading and response to therapy." (PMID 40134607, 2025). "Circulating tumor cells (CTCs) express CXCR4 and promote chemotaxis in response to high concentrations of SDF‐1 in the brain parenchyma for targeted brain metastasis." (PMID 41245887, 2025). "Future studies should explore CXCR4 inhibitors alongside anti-angiogenic, immunotherapeutic, or chemotherapeutic agents to suppress tumor progression." (PMID 41210695, 2025). "CXCR12 guides premetastatic tumour cells expressing CXCR4 to intravasate into circulation through the tumour microenvironment of metastasis (TMEM)." (PMID 40852716, 2025). "The C-X-C chemokine receptor type 4 (CXCR4) is a G protein-coupled transmembrane receptor that contributes to tumor growth and angiogenesis." (PMID 41210695, 2025). "Further, compared to the oe‐NC+M2pep‐Cs NPs/Plerixafor group, the number of Th1 cells significantly decreased; while, the number of Th2 cells significantly increased in the tumor tissues of mice in the oe‐CXCR4+M2pep‐Cs NPs/Plerixafor group." (PMID 40536774, 2025). "Further, compared to the oe‐NC+M2pep‐Cs NPs/Plerixafor group, the number of CD4+ T cells and CD8+ T cells was significantly decreased in the tumor tissues of mice in the oe‐CXCR4+M2pep‐Cs NPs/Plerixafor group." (PMID 40536774, 2025). "Both HIF-1 (activated by hypoxia and reoxygenation after radiotherapy) and stromal cell-derived factor-1 (SDF-1), along with its receptor CXCR4, play a crucial role in recruiting bone marrow-derived cells (BMDCs) to the tumor." (PMID 40141406, 2025).
tumor (continued). "The CXCL12/CXCR4 axis also plays a crucial role in guiding cell migration, particularly in immune cell homing, hematopoietic stem cell mobilization and tumor metastasis." (PMID 40909292, 2025). "CXCR4 blockade can normalise tumour vasculature and reduce hypoxia to sensitise tumours to radiation or a similar angiogenesis inhibitor (such as bevacizumab)." (PMID 41002447, 2025). "Pathogenic IgG targeting glycosylated membrane HSPA4 selectively promotes lymph node metastasis and activates the downstream Src/NF-κB in ITGB5 and tumor cells for CXCR4/SDF1α axis-mediated metastasis." (PMID 41357192, 2025). "Novel drug delivery approaches (e.g., nanoparticles and liposomes) are also being utilised to co-deliver agents targeting CXCR4 and chemotherapy directly to the tumour site, which ameliorates systemic toxicities and increases efficacy." (PMID 41002447, 2025). "Further studies across tumor types and evaluation of CXCR4 expression in stromal T cells are required." (PMID 40849508, 2025). "This apparent contradiction highlights the complexity of CXCR4’s role and its expression patterns in different cellular compartments (circulating vs. tumor-infiltrating) and states (naïve vs. effector T cells)." (PMID 41149503, 2025). "We also established an orthotopic xenograft model by implanting ECs alongside CXCR4-knockdown or control tumor cells at a 1:1 ratio." (PMID 41041071, 2025). "For example, genetically engineered MSCs overexpressing CXCR4 demonstrate enhanced antioxidant stress capacity and improved tumor-targeted migration, which is regulated by the transcription factor nuclear factor erythroid 2-related factor 2 (Nrf2)." (PMID 41301162, 2025). "Compared to the oe‐NC+M2pep‐Cs NPs/Plerixafor group, the fluorescence intensity of CXCR4 in the tumor tissues of the oe‐CXCR4+M2pep‐Cs NPs/Plerixafor group was significantly increased; while, CXCL12 fluorescence intensity remained unchanged." (PMID 40536774, 2025). "CXCR4 is a G-protein-coupled receptor (GPCR) expressed in many different tumour cells, including TNBC." (PMID 41002447, 2025). "Elevated levels of CXCR4 in tumor cells are frequently accompanied by high expression of its ligand CXCL12 within tumor-harboring lymph nodes." (PMID 41149503, 2025). "Studies have further indicated that elevated expression levels of both CXCL12 and CXCR4 correlate with unfavorable prognosis in lymph node-positive cases, as well as with tumor-stroma ratio (TSR) and lymphocytic infiltration at the invasive front (LIR)." (PMID 40943634, 2025). "CXCR4 exerts pleiotropic pro-tumorigenic effects, particularly in supporting tumor growth and proliferation." (PMID 41149503, 2025). "The CXCR4/CXCL12 axis occupies the intersection of intrinsic tumour cell survival, stemness, metastatic dissemination, and immune suppression." (PMID 41002447, 2025). "The CXCL12-CXCR4 signaling axis is crucial not only for tumor progression and metastasis but also for the treatment-induced recruitment of CXCR4-expressing cytotoxic immune cells." (PMID 39997565, 2025). "The interaction of CXCL12 and CXCR4 has a broad impact on tumor cell proliferation, survival, angiogenesis, metastasis, and the tumor microenvironment." (PMID 41149503, 2025). "In summary, CXCR4 antagonists demonstrate the potential to combat therapeutic resistance through blocking tumour-stroma interactions, inhibiting cancer stem cell survival, and increasing immune infiltration." (PMID 41002447, 2025). "Preclinical models show that CSF-1R inhibition reduces TAM infiltration, disrupts M2 programming, and downregulates the CXCL12/CXCR4 axis, an important pathway for tumor cell survival and chemoresistance." (PMID 41228234, 2025). "Immune alterations also include increased CD4 +/CD8 + and IL-17 + γδ T cells, and elevated expression of immunosuppressive (IDO1, IL-10, PD-L1) and oncogenic (AKT1, STAT3, CXCR4) genes with key roles in tumor progression and immune evasion." (PMID 40924302, 2025).